TNF (tumor necrosis factor)
Diseases named in the same sentence as TNF in open-access papers (continued):
Sharing a sentence is not in itself a finding about the gene and the disease.
atherosclerosis (continued). "TNF is one of the most relevant proinflammatory cytokines in the development,progression and complication of atherosclerosis, by reducing the expression ofsynthase endothelial nitric oxide, leading to endothelial dysfunction." (PMID 29944163, 2018). "The overproduction of pro-inflammatory cytokines such as interleukin (IL)-1b, IL-6, and tumor necrosis factor alpha (TNF-α) cause severe adult ailments such as arthritis, allergy, atherosclerosis, and cancer." (PMID 29799460, 2018). "The higher levels of cytokines in CAE, particularly IL-6, IL-8, IFN-γ, IL-1β, and TNF-α are similar to those in atherosclerosis, where TH1 enhances macrophage activation through IFN-γ and IL-2." (PMID 29337902, 2018). "CX3CL1 induces tumor necrosis factor alpha (TNF-α), interferon gamma, and interleukin 1 beta (IL-1β) production in chronic obstructive pulmonary disease, pulmonary hypertension, atherosclerosis, RA, HIV infection, and cancer." (PMID 29268768, 2017). "The present study observed the association between the TNF-α 1031T/C polymorphism and HTLV-I with an increased risk of atherosclerosis-related disease incidence." (PMID 28576445, 2017). "TNFα played a critical role in the promotion of atherosclerosis by decreasing cellular cholesterol efflux from foam cells." (PMID 29029426, 2017). "TRL remnants have been shown to induce endothelial cell apoptosis via increased secretion of the proapoptotic cytokines, tumor necrosis factor-α (TNF-α), and interleukin-1 β (IL-1β), a process which can contribute to vascular injury and atherosclerosis." (PMID 29212549, 2017). "Atherosclerosis is generally accepted to be a chronic inflammatory disease in which the pro-inflammatory cytokines interleukin (IL)-1β and tumor necrosis factor (TNF)-α play an important role." (PMID 28235036, 2017). "Herein, ICAM-1, VCAM-1, MCP-1, TNF-α, IL-1β, and MMPs-9, which participate in initial and later stages of atherosclerosis, will be more elaborately discussed." (PMID 29038791, 2017). "The “inflammatory theory” of atherosclerosis highlights the key role of specific cytokines, particularly tumour necrosis factor-alpha (TNF-α), interleukin-1 (IL-1), and interleukin-6 (IL-6), in disrupting endothelial integrity and vascular homeostasis." (PMID 29430085, 2017). "Taken together, our data suggested TAK1/p38 MAPK/eNOS pathway is involved with protecting endothelial cells against atherosclerosis through depressing cellular oxidative stress stimulated by TNFα." (PMID 29029426, 2017). "Intermediate CD14++CD16+ monocytes selectively express C–C chemokine receptor type 5 (CCR5), secret more inflammatory cytokines such as tumor necrosis factor-α and interleukin-1β, and have been shown to drive atherosclerosis." (PMID 28789689, 2017). "Previous findings have demonstrated that DHEA-S affects atherosclerosis by improving endothelial cell growth and survival and inhibiting TNF-α production, which is a primary factor in endothelial dysfunction." (PMID 29312152, 2017). "Glibenclamide suppressed phosphorylation of NF-κB, ERK 1/2, and JNK in RAW264.7 cells and reduced the release of TNF-α, which alleviated the progression of atherosclerosis in mice." (PMID 29178967, 2017). "Leptin also stimulates the secretion of inflammatory markers such as CRP, TNF-α and IL-6, which are directly involved in the development of endothelial dysfunction and atherosclerosis." (PMID 27598978, 2017). "Inflammatory cytokines including tumor necrosis factor α (TNFα) and interleukin-1β are elevated in atherosclerosis." (PMID 28646109, 2017). "The cytokine TNF-α is an important mediator of acute inflammatory processes that occur during the progression of atherosclerosis." (PMID 29354066, 2017). "NF-kB controls the expression of genes that direct the initiation and progression of atherosclerosis or fibrosis, including cytokines, such as TNFα or IL-1β." (PMID 28272516, 2017).
atherosclerosis (continued). "It is accepted that the TNFα signaling is a central pro-inflammatory pathway involved in atherosclerosis progression." (PMID 28779156, 2017). "TNF-α is responsible for blood vessel malfunctions in the pathogenesis of atherosclerosis, type 2 diabetes complications and preeclampsia." (PMID 29170479, 2017). "Transforming growth factor beta-activated kinase 1 (TAK1) plays a critical role in TNFα-induced atherosclerosis via endothelial nitric oxide (NO) synthase (eNOS) uncoupling and NO reduction." (PMID 29029426, 2017). "TNF-α boosts atherosclerosis development by promoting the transcytosis of low-density lipoprotein (LDL) across endothelial cells, thus contributing to the reservoir of LDL in vascular walls." (PMID 29348768, 2017). "Researches indicate that circulating levels of TNF-α are increased in advanced atherosclerosis and in patients symptomatic for acute stroke." (PMID 29038791, 2017). "Specifically, Uch-L1 decreased the NF-κB activity induced by TNF-α and increased eNOS expression, which was able to protect atherosclerosis reducing ischemic vascular disease." (PMID 29033830, 2017). "A recent study has showed TNF-α overexpression increased expression of JAM-1, which promoted the chemotaxis and exudation of cells to cause atherosclerosis." (PMID 29212549, 2017). "IL-17C and TNF-β, elevated in AD, have overlapping signaling pathways with IL-17A/F and TNF-α, which are thought to contribute to atherosclerosis in psoriasis." (PMID 28821884, 2017). "High levels of tumor necrosis factor (TNF) and IL-6 associated with RA are also significantly associated with the development of atherosclerosis." (PMID 27736998, 2016). "TNF-α is one of such cytokines which is released from macrophages upon oxLDL incubation and fires many pro-inflammatory processes in early atherosclerosis." (PMID 27467817, 2016). "In summary, our study demonstrates that DCs are involved in the accelerated endothelial inflammation and atherosclerosis partly because of the released exosomes, which activate endothelial cells via TNF‐α mediated NF‐κB pathway." (PMID 27515767, 2016). "Disruption of the TNF-α gene locus in different experimental mouse models consistently revealed diminished lesion progression and demonstrated that TNF-α is actively involved in the progression of atherosclerosis." (PMID 27467817, 2016). "Dysregulation, especially overproduction of TNF-α, has been found in a variety of human diseases including atherosclerosis, cancer, atherosclerosis and inflammatory bowel disease." (PMID 27187381, 2016). "That VPO1 in aorta is stimulated by LPS or TNF-α sheds light on the studies of hPx enzymes and atherosclerosis." (PMID 27167346, 2016). "TNF-α is a well-known inflammatory cytokine involved in the onset as well as the progression of atherosclerosis that induces the expression of transcriptional factors, such as the nuclear factor-κB." (PMID 27711199, 2016). "Vascular inflammation is recognized as the foundation mechanism of atherosclerosis, and proinflammatory mediators including IL-6, TNF-α, and MMP-9 play a pivotal role in atherosclerosis." (PMID 27403152, 2016). "Our study demonstrates that mature DCs derived exosomes increase endothelial inflammation and atherosclerosis via membrane TNF‐α mediated NF‐κB pathway." (PMID 27515767, 2016). "Pro-inflammatory cytokines, especially tumor necrosis factor-alpha (TNF-α), play an important role in inflammation, and have been shown to increase endothelial inflammation and atherosclerosis." (PMID 27881110, 2016). "Other proinflammatory cytokine is the tumor necrosis factor-alpha, several evidence show that is a key contributor in the development, progression, and complications of atherosclerosis." (PMID 26751459, 2016). "Recently, another study has reported the potential role of TNF-α in pathogenesis of atherosclerosis and plaque formation and its role in plaque vulnerability in carotid arteries." (PMID 27271180, 2016).
atherosclerosis (continued). "The obtained results demonstrated that production of proinflammatory TNFα was significantly lower in atherosclerosis patients and significantly higher in cancer patients in comparison to healthy subjects." (PMID 26885534, 2016). "It attenuates atherosclerosis by inhibiting NF-κB activation and so reducing levels of superoxide and tumor necrosis factor (TNF)-α with a significant elevation of cAMP expression in the mice fed cilostazol-supplemented high fat diet." (PMID 25992691, 2015). "Macrophages produce abundant amounts of pro-inflammatory cytokines, such as TNF-α, IL-6, and IL-1β, to promote atherosclerosis." (PMID 26045945, 2015). "These include in particular Th1-cell lineage which are pro-atherogenic via the secretion typically of IFN-γ and TNF-α, and Th2-cell lineage secreting IL-4, IL-10 and IL-13 whom their role in atherosclerosis remains controversial, including Th1 and Th2 cells." (PMID 26600018, 2015). "Inflammation is an important risk factor for atherosclerosis and EAT secretes various cytokines including IL-1β, IL-6, and TNF-α, the levels of which were significantly higher in patients with coronary artery disease." (PMID 25887962, 2015). "Recently, numerous basic research studies have indicated that TNF-α accelerates atherosclerosis in mice." (PMID 26580653, 2015). "The MAN1A2 gene, which was in this gene set, was reported to be down-regulated by TNFα and is part of an inflammatory mechanism in the pathological process of atherosclerosis." (PMID 25958224, 2015). "TNF-α plays a key role in the regulation of inflammatory processes in atherosclerosis, mainly through the TNF-receptor 1 (p55) signaling pathway." (PMID 25574216, 2015). "The released NF-κB dimers enter the nucleus and activate the expression of many genes involved in the initiation and progression of atherosclerosis, including cytokines (e.g., TNF, IL-6), adhesion molecules (e.g., VCAM-1, ICAM-1) and chemokines (e.g., MCP-1)." (PMID 26322890, 2015). "It is also well known that TNF alpha is crucially involved in the pathogenesis and progression of atherosclerosis." (PMID 25699123, 2015). "The laboratory indices of microinflammation include elevated blood levels of CRP and some cytokines, mainly IL-6, IL-18, IL-10, and TNF-alpha, which correlated with acceleration of atherosclerosis." (PMID 26236736, 2015). "Atherosclerosis is a hyperlipidemia-induced chronic inflammatory process of the arterial wall, involving interleukins (ILs) such as IL-1β, IL-6, tumor necrosis factor (TNF)-α, and C-reactive protein (CRP)." (PMID 25664324, 2015). "Hyperglycemia markedly increased TLR-4 mRNA and protein expression in macrophages of atherosclerotic lesions and increased levels of NF-κB that promoted inflammatory cytokines (TNF-α, IL-1ß, and adhesion molecules) leading to atherosclerosis." (PMID 25826421, 2015). "Another aspect of atherosclerosis-related inflammation that is induced by TNFα is the alteration in endothelial permeability." (PMID 26578976, 2015). "TNF-α is a pro-inflammatory cytokine that is released in atherosclerosis and has been reported to promote the process of atherosclerosis." (PMID 26095681, 2015). "There were no positive correlations of the other inflammatory markers evaluated (TNF-α, IL-6, IL-1β, homocysteine, hsCRP) in relation to the imaging markers of subclinical atherosclerosis." (PMID 26382922, 2015). "Endothelial dysfunction is the first event in atherogenesis pathway and the induction of this stat by TNFα is, at least in part, responsible for the increased incidence of atherosclerosis-related events in obese patients." (PMID 26578976, 2015). "Dietary flax seed is reported to suppress the production of TNF-α in hypercholesterolemic atherosclerosis in rabbits." (PMID 25822525, 2015). "In the early stages of atherosclerosis, TNF-α release from macrophages is a crucial initiation step that leads to the disruption of endothelial junctions and the facilitation of monocyte transmigration." (PMID 26367277, 2015).
atherosclerosis (continued). "Di(2-ethylhexyl) phthalate (DEHP) has been shown to induce atherosclerosis by increasing tumor necrosis factor (TNF)-α, interleukin (IL)-6, and intercellular adhesion molecule (ICAM) productions." (PMID 26690114, 2015). "The aims of this study were thus to evaluate levels of inflammatory markers of atherosclerosis, such as IL-6, TNF-α, CRP, and PTX-3 in a sample of OSA patients; to assess the correlation between carotid IMT and levels of these inflammatory markers." (PMID 24481114, 2014). "Meanwhile, impaired endothelial cells and foam cells can release proinflammatory cytokines such as IL-6 and TNF-α, which can enlarge vascular inflammation and accelerate the development of atherosclerosis." (PMID 25210730, 2014). "Individuals with atherosclerosis displayed higher TNF secretion, both constitutively and after stimulation." (PMID 25329381, 2014). "The phenotypic modulation of VSMCs from a contractile to synthetic state plays an important role in the development of atherosclerosis, which is modulated in part by inflammatory cytokines like TNFα." (PMID 25384061, 2014). "PGRN also played a protective role in atherosclerosis through suppressing TNFα-induced expression of ICAM-1 and VCAM-1 in endothelial cells." (PMID 24651300, 2014). "In particular, we found high levels of IL-1β, TNF-α, IFNγ and CD40L, all of which have been associated with the progression of atherosclerosis." (PMID 25548922, 2014). "In concert with our finding, the clinical relevance studies revealed that PPAR-α agonist fenofibrate decreased plasma concentration of IL-6 and TNF-α in patients suffering atherosclerosis." (PMID 24465540, 2014). "Th1 cells, which produce interferon-γ and tumor necrosis factor-α, are effective in eliminating intracellular pathogens and have a proinflammatory and proatherogenic role in atherosclerosis." (PMID 24558316, 2014). "Since our main objective was to associate the membrane expression of CD36 with subclinical atherosclerosis, other molecules related with cardiovascular risk such as ox-LDL, IL-6, and TNFα were tested.Results." (PMID 25006585, 2014). "The inflammatory process, mediated through pro-inflammatory cytokines such as tumor necrosis factor (TNF), is linked to atherosclerosis and plaque rupture and has confounding effects on lipid and glucose metabolism, blood pressure and hemostatic factors." (PMID 25381560, 2014). "De-differentiation of vascular smooth muscle cells (VSMCs) plays a critical role in the development of atherosclerosis, a chronic inflammatory disease involving various cytokines such as tumor necrosis factor-α (TNFα)." (PMID 25384061, 2014). "Inhibition of TNFα or depletion of the TNFα gene reduces the progression of atherosclerosis in ApoE−/− mice." (PMID 25105129, 2014). "The main inflammatory cytokines participating in atherosclerosis, IL-1β, TNF-α, MCP-1 and MMP-2, were detected in the plaque." (PMID 24755612, 2014). "As recently reviewed, TNFα and LPS stimulated monocyte adhesion to endothelial cells are initiating events in the pathogenesis of atherosclerosis." (PMID 24835252, 2014). "In atherosclerosis, LTB4 can induce the overexpression of TNF-α, IL-6 and MCP-1 mRNA in cultured monocytes, causing an inflammatory environment." (PMID 25229347, 2014). "Cytokines, such as TNF-α and IL-6, are primarily involved in the early stages of the inflammatory response culminating in atherosclerosis." (PMID 24741576, 2014). "It has been previously shown that co-stimulatory molecules of the B7/CD28 and tumor necrosis factor (TNF)/TNF receptor family are instrumental in T cell activation during atherosclerosis." (PMID 24691202, 2014). "TNFα promotes atherosclerosis through the inhibition of cholesterol efflux, favoring the cholesterol uptake by CD36 and other SR via protein kinase pathway." (PMID 25006585, 2014).
atherosclerosis (continued). "Proinflammatory cytokines, such as tumor necrosis factor-α (TNF-α) and interleukin-6, have been implicated in the initiation and maintenance of the systemic and vascular inflammation that is associated with atherosclerosis." (PMID 25299643, 2014). "Fenofibrate treatment reduces the plasma concentrations of fibrinogen, IL-6, CRP, interferon-γ, and tumor necrosis factor (TNF)-α in patients with hyperlipidemia and atherosclerosis." (PMID 25090113, 2014). "Studies demonstrated that increased serum levels of C-reactive protein (CRP), interleukin (IL)-6, tumor necrosis factor (TNF)-α, and pentraxin (PTX)-3 are important risk factors for atherosclerosis, and cardiovascular diseases." (PMID 24481114, 2014). "It is notable that IL-1β, IL-18, TNF-α, and IFN-γ play critical pathogenic roles in atherosclerosis, and increased levels of these cytokines are associated with the onset of ACS." (PMID 24733959, 2014). "TNF-α plays an important role in the inflammation/atherosclerosis cascade, it acts as pro-inflammatory marker." (PMID 24891839, 2014). "We demonstrated that elevation of APN levels suppressed aortic expression of key inflammatory genes (TNF-α, IL-6, IL-12) in a hypertensive, pro-inflammatory and hyperlipidemic model of atherosclerosis." (PMID 24466075, 2014). "By producing pro-inflammatory factors such as TNFα and IL-6, M1 macrophages are able to drive the inflammatory reaction and thereby enhance the development of atherosclerosis." (PMID 25347070, 2014). "Given the evident role of TNF in atherosclerosis, a beneficial effect of TNF inhibition has been postulated; however, observational studies and data form registries did not always demonstrate a decrease in cardiovascular events." (PMID 24222719, 2013). "Secondly, atherosclerosis in these animals was characterized by a marked increase in plasma TNF-α and IL-6, which upregulation was successfully suppressed by celastrol treatment." (PMID 23799016, 2013). "In that study, exogenous progranulin suppressed interleukin-8 (IL-8) production from VSMCs, but knockdown of progranulin increased TNF-α-induced IL-8 secretion, an important cytokine involved in the progression of atherosclerosis." (PMID 24098801, 2013). "Flavanones can also modulate inflammatory process in atherosclerosis by reducing the binding of monocytes treated with Naringenin and Hesperitin, flavanones found primarily in citrus fruits, to TNFα activated endothelial cells." (PMID 24077237, 2013). "As has mentioned in Background, TNF-α and IL-1β are two important inflammatory factors in the progression of atherosclerosis." (PMID 23895132, 2013). "Given the pivotal role of TNF in the pathogenesis of both RA and atherosclerosis, we aimed at investigating the effect of TNF inhibition on markers of endothelial function." (PMID 24222719, 2013). "The results of previous studies have demonstrated that hs-CRP, TNF-α and IL-6 levels correlate with coronary heart disease, myocardial depression, atherosclerosis, left ventricular dysfunction and other factors." (PMID 24137221, 2013). "TNF-α is an important pro-inflammatory cytokine which is involved in endothelial cell (EC) dysfunction and atherosclerosis by down-regulating endothelial nitric oxide synthase (eNOS) expression." (PMID 24010774, 2013). "There are contradictory reports regarding the association between adiponectin and sVCAM-1; adiponectin was found to suppress the adhesion of monocytes to endothelial cells by decreasing the TNF-α-mediated expression of sVCAM-1, thus reducing atherosclerosis." (PMID 24224162, 2013). "PPAR-γ controls the expression of paraoxonase that are shown to decrease inflammatory factors involved in the development of atherosclerosis (such as IL-1, IL-6 and TNF-α)." (PMID 23437105, 2013). "The significant reduction of elevated VCAM-1, MCP-1, TNF-α, IL-17 in atherosclerosis model of hypercholesterolemia rabbit shows the effect of clopidogrel on such inflammatory markers." (PMID 24455725, 2013).